CASP9 (caspase 9)
Diseases named in the same sentence as CASP9 in open-access papers (continued):
Sharing a sentence is not in itself a finding about the gene and the disease.
lung carcinoma (continued). "Notably, we found that juglanin could induce both intrinsic and extrinsic pathways to enhance apoptotic response in lung cancer cells, proved by the elevated Bad/Bax/Caspase-9 and TRAIL/FADD/Caspase-8, respectively." (PMID 29212196, 2017). "Taken together, TIPE2 promoted lung cancer cell apoptosis through affecting apoptosis-related molecules caspase-3, caspase-9, Bcl-2 and Bax, possibly via regulating P38 and Akt pathways, indicating that TIPE2 might be a novel marker for lung cancer diagnosis and therapy." (PMID 25946186, 2015). "DMC induces apoptosis in lung cancer (A549) and bladder cancer (RT4 and TCCSUP) cells by activating Caspase-3 and Caspase-9 activity, and inhibiting the expression of anti-apoptotic proteins (Bcl-2 and Bcl-xL)." (PMID 40490812, 2025). "Simultaneously, an increase in cytochrome C and an enhancement of caspase-9 and caspase-3 activities were observed in A549 and PC9 lung cancer cells." (PMID 37762572, 2023). "For example, PES treatment induces caspase-3 and caspase-9 activation, eventually activing expression of cleaved PARP in lung cancer." (PMID 32110810, 2020). "The cleavage of caspase 9 and PARP further supports that 7-epi-clusianone induces apoptosis in NCIH460 lung cancer." (PMID 31816878, 2019). "We found that IFN-γ-induced apoptosis in lung cancer cells shared the similar apoptotic process as BEAS-2B, including the release of cytochrome C and the activation of Caspase-9, Caspase-3, and PARP." (PMID 31501431, 2019). "The caspase 9 (CASP9) gene has two antagonistic isoforms, proapoptotic Casp9a and prosurvival Casp9b, and its splicing is dysregulated in NSCLC lung cancer cell lines." (PMID 23766705, 2013). "Expression of Bcl-2, cleaved caspase-3, caspase-9 and PAPP proteins in A549 lung cancer cells and the A549 xenograft BALB/c nude mice model was determined by Western blot." (PMID 22866867, 2012). "In H522 lung cancer cells, HSP induced apoptosis by initiating the Fas death receptor/extrinsic pathway, which led to the dose-dependent upregulation of Bax, caspase-3, and caspase-9." (PMID 40427522, 2025). "Furthermore, to delineate the contribution of caspases in FDN-mediated apoptosis in lung cancer, A549 cells were pretreated for 2 h with Z-DEVD-FMK (caspase-3 inhibitor) and Z-LEHD-FMK (caspase-9 inhibitor) prior to treatment with FDN (50–200μM) for 24 h." (PMID 35054507, 2022). "Additionally, it has been reported that the PI3K/AKT pathway is involved in blocking apoptosis in lung cancer cell lines; p-AKT increases radioresistance by inhibiting the pro-apoptotic proteins BAD, BAX, and caspase-9." (PMID 34760374, 2021). "In vitro anti-lung cancer studies revealed that SC, SCA, SCH, and SCAH decreased MMP, decreased Bcl-2 expression, increased the release of cytochrome c, increased activation of caspase-9 and -3, and increased late apoptosis of A-549 cells." (PMID 32604764, 2020). "Combined with these results, we speculate that TIPE2 promotes lung cancer cell apoptosis through activation of P38 MAPK, which triggers the over-expression of caspase-3 and caspase-9." (PMID 25946186, 2015). "The data showed that PTL could induce cleavage of apoptotic proteins such as CASP8, CASP9, CASP3 and PARP1 both in concentration- and time-dependent manner in tested lung cancer cells, indicating that apoptosis was trigged after PTL exposure." (PMID 24387758, 2014). "In lung cancer, luteolin confirms its ability to interfere with cancer progression and development, by inhibiting migration of NSCLC cells and inducing apoptosis, through the incremented activation of Caspase-3 and Caspase-9, decreased Bcl-2 and increased Bax expressions." (PMID 38203299, 2023).
lung carcinoma (continued). "In lung cancer and gastric cancer, miR-1269a can also promote tumor cell proliferation and cell cycle progression and inhibit tumor cell apoptosis by activating the PI3K/AKT signaling pathway and inhibiting the caspase-9-mediated apoptotic pathway, respectively." (PMID 35252180, 2022). "Caspase-9 was activated in A549 cells after treatment with AZD2014 or AZD2014 combined with 2DG, suggesting the involvement of mitochondrial apoptotic pathway in the apoptosis induced by mTOR inhibitor alone and combined with glycolysis inhibitor in lung cancer cells." (PMID 26176608, 2015). "We demonstrated that inhibition of caspase-9 in lung cancer cells could not be attributed to abnormal expression of Apaf-1 and procaspase-9 or to genetic alterations in the procaspase-9 coding sequence analysed in NSCLC H460 cells." (PMID 16796750, 2006). "Among others, these include CASP9 and CDC42 (1p36), which have already been studied in neuroblastoma; CACNA2D3 (3p21-p22), which was recently proposed as a tumor suppressor gene in lung cancer; IGSF4 (11q23), which is a known tumor suppressor gene in several cancers; and DLK1 (14q)." (PMID 16989664, 2006). "Similarly, the DPT-C9h peptide did not have any apoptotic effect on the mouse lung cancer cell lines LKR10 and LKR13, while the peptide DPT-C9, specific for mouse caspase-9, induced apoptosis in both cell lines upon 24 h of treatment." (PMID 23637769, 2013). "Although, TUCAN does not seem to act as a caspase-9 inhibitor, its differential expression in NSCLC versus SCLC cells suggests that TUCAN may play a role in the lung cancer biology, specifically in the NSCLC subtype." (PMID 16796750, 2006).
melanoma (93 papers, 2011 to 2025). A malignant, usually aggressive tumor composed of atypical, neoplastic melanocytes. "(2010), it was stated that Caspase-9 causes apoptosis in melanoma cells through mechanisms such as endoplasmic reticulum stress, changes in mitochondrial membrane potential and ROS activation." (PMID 40040652, 2025). "For example, astragalin demonstrates cytotoxic properties and apoptosis induction by modulating critical melanoma-associated proteins such as caspase-9/3 and SOX10." (PMID 40508400, 2025). "Both F10503LO1 and F21010RS1 decreased the content of phospho-AKT, at the time that activate PARP and caspase 9 and 3, all mechanisms compatible with the observed loss of viability of the melanoma cells." (PMID 30191142, 2018). "These processes have all been associated with DNA damage accumulation and implicated in melanoma, where suppression of Caspase-9 and p16 and over-stimulation of LCB3 have been linked to melanomagenesis, contributing to disease progression and resistance to therapy." (PMID 40182046, 2025). "In both melanoma cells, Bcl-2 protein levels were reduced by 3.6-fold and the levels of Bax, caspase-9, and caspase-3 were induced by 4.6-, 3.9-, and 4.3-fold in A375 cells, respectively." (PMID 40063190, 2025). "As a result of the combination treatment, Bcl-2, an anti-apoptotic protein, decreased in both melanoma cell lines, while a significant increase was observed in pro-apoptotic Bax and pro-apoptotic caspase-9 and caspase-3 protein levels." (PMID 40063190, 2025). "This dual inhibition of TrxR1 and XIAP in melanoma cells induces substantial caspase-9/caspase-3 activation, leading to irreversible GSDME-mediated pyroptosis." (PMID 40486906, 2025). "In conclusion, these results suggest that TRI-03 primarily induces pyroptosis in melanoma cells through the activation of the caspase-9/caspase-3/GSDME signaling pathway." (PMID 40486906, 2025). "This supports research showing that DZN administration raised Bax and activated caspase-9 and caspase-3 in melanoma cells, indicating that the combination triggers apoptosis via the intrinsic mitochondrial route." (PMID 40217305, 2025). "Honeybee venom and melittin, a main component of honeybee venom, inhibited the growth of melanoma cells by inducing apoptosis through the upregulation of caspase-3 and caspase-9." (PMID 38671917, 2024). "-EGCG treatment of melanoma cells results in increased levels of pro-apoptotic Bax and the activation of caspase-3, caspase-7, and caspase-9." (PMID 39329914, 2024). "The changes in caspase-3 and caspase-9 enzyme activities were compared between control and UA-treated A-375 melanoma cells." (PMID 39473730, 2024). "The effects of UA on caspase-3 (executer) and caspase-9 (initiator) enzyme activities in A-375 melanoma cells were evaluated." (PMID 39473730, 2024). "Genes in cluster 8 (GSTO2, LRRC34), 9 (CLPTM1L) and 10 (CTSS, SETDB1, ANXA9, GOLPH3L, HORMAD1, PPIL3, CASP9, ALS2CR12) underlie the association between melanoma and cancers." (PMID 38308491, 2024). "APAF-1 gene dysregulation is often indicated (42%) as one of the factors inhibiting the apoptotic process in melanoma cells; namely, by directly preventing caspase-9 activation and initiation of the protease cascade." (PMID 39770908, 2024). "Our data showed that FXT induced an increase in the expression of BAX, Bad, and caspase-9 in melanoma cells, which are key events in the process of cell apoptosis." (PMID 38911391, 2024). "The suppression of human A375 melanoma cells by ascorbate treatment and caspase-3 and caspase-9 activation, as well as induction of the Bcl-2- and Bax-mediated mitochondrial pathway, was already described by Chen and coworkers." (PMID 36672190, 2023). "A promising strategy to inhibit melanoma progression has been found for the combination of DM-1, a curcumin analog, and dacarbazine in B16F10 melanoma-bearing mice by the activation of apoptosis with the cleavage of caspase-3, caspase-8, and caspase-9." (PMID 36829966, 2023).
melanoma (continued). "This is consistent with previous results that celecoxib, another cox 2 inhibitor, induces apoptosis through an intrinsic pathway by overexpression of the cleaved caspase 9 in the melanoma cell line." (PMID 37760972, 2023). "Caspase-9 dominated in A375 melanoma cells, while caspase-8 was mainly activated in the C32 cell line." (PMID 35055021, 2022). "Caspase-9 (apoptosis-related protein) and Bcl-XL (anti-apoptotic protein) were significantly up and downregulated, respectively, in melanoma-treated cells." (PMID 35684471, 2022). "Cleavage of caspase-9, an indicator of activation of the caspase cascade, was greatly increased in both MeWo and A375 melanoma cells treated with HuR-NP compared to C-NP-treated and untreated control cells." (PMID 33418925, 2021). "From in vitro experiments of hispidulin against melanoma, it was found that hispidulin effectively activates caspase 8 and caspase 9, as well as increases the expression of cleaved caspase 3 and cleaved PARP." (PMID 34356663, 2021). "The qRT-PCR was performed to evaluate the expression levels of matrix metallopeptidase 3 (MMP-3), SMAD2, SMAD3, caspase-8, caspase-9, and miR-214 in order to reveal the rCTII-induced signaling pathways in melanoma." (PMID 33167431, 2020). "Clear activation of caspase 7 and caspase 9 after ACF treatment also indicated that this drug induced cell death in melanoma cells under normoxic conditions." (PMID 33396270, 2020). "After treating melanoma cells with rCTII, the ratio of caspase-8/caspase-9 was 2.513, highlighting the dominance of the intrinsic pathway of apoptosis." (PMID 33167431, 2020). "While andrographolide enhanced the expression of Bax, caspase-3, and caspase-9, it down-regulated that of Bcl-2, leading to apoptosis in melanoma B16F-10 cells, and it promoted apoptosis in pancreatic cancer cells via inhibition of STAT3 and Akt activation." (PMID 31404237, 2019). "Cell death was suppressed in cells treated with either of these two inhibitors, suggesting that bornyl cis-4-hydroxycinnamate-induced apoptosis is mediated by caspase-3 and caspase-9 in melanoma cells." (PMID 29734677, 2018). "Studies have shown that apoptosis induced by HVJ-E infection is associated with the activation of caspase-8 in PC3 human prostate cancer cells and the activation of caspase-9 in murine B16F10 melanoma cells." (PMID 30534001, 2018). "The same strategy was used to improve the affinity of the Melanoma IAP protein for Caspase-9, and the resulting chimera was then successfully used for the development of Melanoma IAP antagonists." (PMID 27725183, 2016). "To understand the mechanisms of cell death, we performed western blot analyses of protein expressions in melanoma cells, which pointed out that both extracts induced caspase-3 and caspase-9, both of which have vital roles in apoptosis." (PMID 27403230, 2016). "The loss of ΔΨm, activation of caspase 9 and 3, followed by cleavage of PARP are characteristics of intrinsic apoptosis, and were observed upon incubation of N-Br and N-I with melanoma cells." (PMID 26503030, 2015). "Indeed, the average expression of caspase 9 in treated melanomas was found to be higher than the corresponding expression in the control melanoma cultures." (PMID 40563555, 2025). "S2 human melanoma cells by inducing apoptosis through increasing the expression of apoptotic protein Bax and reducing the expression of anti-apoptotic protein Bcl-2 and also through the activation of caspase-9 and caspase-3." (PMID 39478959, 2024).
melanoma (continued). "Thus, the stimulation of LC3A/B was observed only in amelanotic melanoma cells with high levels of caspase-9 activity." (PMID 35055021, 2022). "Recent studies demonstrated that caspase-9 could be activated by the Tom20/Bax/Cytochrome c pathway in melanoma or by lobaplatin/ROS and JNK phosphorylation/Bax/Cytochrome c pathways in colon cancer, showing a great potential value of clinical application." (PMID 35401700, 2022). "In addition, p32 knockdown in melanoma cells showed an increased cleaved PARP and caspase 9 level which are hallmark of apoptosis, Suggesting the inhibition of p32 expression in melanoma cells reduces the tumorigenicity by increasing the apoptosis." (PMID 34711805, 2021). "In melanoma cell lines, the apoptotic process triggered by WFA involved the mitochondrial pathway and was associated with Bax mitochondrial translocation, cytochrome-c release, transmembrane potential changes, and caspase 9 and caspase 3 activation." (PMID 33184347, 2020). "Additionally, many studies have suggested that the mechanism of action of MBZ as an anti-tubulin drug in cancer cells is mediated by its effect on caspase-3 and caspase-9 in different tumour types, such as melanoma and breast cancer." (PMID 31836811, 2019). "Additionally, chaetocin treatment significantly up-regulated the protein levels of Bax, cleaved caspase-9/-3, simultaneously down-regulated the protein levels of Bcl-2, procaspase-9/-3, and activated caspase-9/-3 activity in the melanoma cells." (PMID 28419143, 2017). "In PM-WK cells, survivin, an inhibitor of apoptosis that is overexpressed in melanoma and blocks activation of caspase-9, is downregulated after 72 hrs of exposure to T-oligo, with subsequent decrease of the caspase-9, caspase-3, and caspase-7 proenzymes after 96 hrs of treatment with T-oligo." (PMID 23800953, 2013). "Furthermore delNS1 viruses induced activation of caspase 9 and to a minor extent caspase 8, suggesting that both, intrinsic and extrinsic apoptotic pathways are triggered in infected melanoma cells." (PMID 22563505, 2012). "Moreover, to determine whether SFN-induced apoptosis in melanoma cells is caspase-dependent, caspase-8, caspase-9 and caspase-3 expression was assessed." (PMID 28864908, 2018). "To explore whether HHT-induced alternative splicing has potential relevance in cancer treatment, we examined the effect of HHT on the alternative splicing of Bcl-x and Caspase 9 in human non-small cell lung cancer A549 cells and human malignant melanoma UACC903 cells." (PMID 29788973, 2018). "In addition, treatment of A375.S2 melanoma cells with cudraflavone C resulted in a decrease in the mitochondrial membrane potential (as determined by the JC-1 assay), and induced activation of caspase-9 and caspase-3/7." (PMID 28703746, 2017). "Thus, the activity of caspase-3 and caspase-9 in VS-5584-treated melanoma cells was tested." (PMID 26204252, 2015). "Western blot analysis revealed GEF-induced caspase-9 and -3 activation, PARP cleavage, and Bcl-2 downregulation, suggesting induction of apoptosis by GEF in melanoma cells." (PMID 39941974, 2025). "Researchers observed apoptosis associated with the activation of caspase-3, caspase-7, caspase-8 and caspase-9, as well as cleavage of BID and PARP, which is similar to our results of MZB activity against melanoma cells." (PMID 39057424, 2024). "Specifically, in amelanotic malignant melanoma cells, EGCG led to a significant increase in active caspase-3 and caspase-9, while caspase-7 levels were only slightly elevated." (PMID 39329914, 2024). "FXT promotes the apoptosis process in melanoma cells by influencing the expression of key proteins such as γ-H2AX, Akt, BAX, Bad, and caspase-9." (PMID 38911391, 2024). "Pterostilbene induced apoptosis in amelanotic C32 melanoma cells, and this effect was mediated by an increase in the expression of the BAX, CASP9, and CASP9 genes; induction of caspase 3 activity; and DNA degradation." (PMID 36674631, 2023).